CASP14 (caspase 14)
Diseases named in the same sentence as CASP14 in open-access papers (continued):
Sharing a sentence is not in itself a finding about the gene and the disease.
Salmonella Infections (1 paper, 2025). Infections with bacteria of the genus SALMONELLA. "CASP14 and S100A10 are involved in Salmonella infection (P = 0.2076)." (PMID 40029616, 2025).
squamous cell carcinoma (1 paper, 2021). A carcinoma arising from squamous epithelial cells. "The global gene expression profiles of normal murine epidermis and UV-induced squamous cell carcinomas (SCCs) in mice showed an 8-fold lower expression of caspase-14 in squamous cell carcinoma." (PMID 34070382, 2021). "In the murine model, the expression of caspase-14 mRNA was reduced in squamous cell carcinoma induced by UVB." (PMID 34070382, 2021).
cancer (12 papers, 2018 to 2025). A tumor composed of atypical neoplastic, often pleomorphic cells that invade other tissues. "The dysregulation of the expression of caspase-14 was described in neoplastic human cells and in several cancer cell lines." (PMID 34070382, 2021). "Cancer development was observed by the modulation of genes involved in cell death (HIST1H1T, CASP14, and DNAJC3), cancer related genes (WNT8A and CASC8), gene expression (transcription) (ZNF570 and ZFP42), and metabolism of proteins (CALB2 and KLHDC3)." (PMID 31797963, 2019).
tumor (10 papers, 2006 to 2025). "Considering that activation of caspase 8 has been associated with CDDO-induced killing in human tumor cells, it is conceivable that caspase 14 plays a similar role in apoptosis induction in mouse iMycEμ cells." (PMID 16759389, 2006). "We and other groups identified a few tumor suppressors, p18 and caspase 14 27, 36, 40, as well as oncogenes, cyclin D and c-Myc 39, 55, as critical targets of GATA3 in controlling mammary or lymphoid cell proliferation." (PMID 34976209, 2022). "The overexpression of caspase-14 significantly decreased cell proliferation, delayed tumor growth, and induced the expression of three squamous differentiation markers in A431 cells, epidermal cancer cell line model cells." (PMID 34070382, 2021). "An interesting introduction to the analysis of caspase-14 in neoplastic cells was presented in 2005 in research, including few neoplasm types and caspase-14 testing via the immunohistochemical examination of tissues." (PMID 34070382, 2021). "We have recently shown the exogenous expression of caspase-14 in tumor cells blocks tumor growth through inhibition of angiogenesis." (PMID 22876114, 2012). "Consistent with a possible tumor-suppressing function in skin, Casp14 was recently shown to be down-regulated in UV-induced skin carcinogenesis." (PMID 16759389, 2006). "In humans, caspase 14 is mainly found in epidermal cells, in which it can be induced by epigallocatechin-3-gallate, the most abundant tumor-preventive polyphenol in green tea." (PMID 16759389, 2006). "Oral cavity squamous carcinoma presented the reduced expression of caspase-14 in 47% of tested tumors and was not related to keratinization, tumor differentiation, or HPV infection." (PMID 34070382, 2021). "Additionally, we observed that clusters 6, 7, 9 and 13 (CASP14, PRSS27, CALML5), which were enriched in CC, manifested high expression levels of genes related to carcinogenic pathways such as epithelial‐to‐mesenchymal transition, tumour cell proliferation, migration, invasion and angiogenesis." (PMID 36967539, 2023).
infection (5 papers, 2018 to 2022). The state of being infected such as from the introduction of a foreign agent such as serum, vaccine, antigenic substance or organism. "During instances of external infection or irritation, CASP14 expression is affected and downregulated, leading to a decrease in substances that maintain the skin barrier structure, such as FLG and natural moisturizing factors." (PMID 34799820, 2022). "Another possibility is that the increased expression of the CASP14 gene is involved in the repair of damage caused by the repression of the FLG and KRT1 genes as a host defense response during infection with T. rubrum." (PMID 30029541, 2018). "During the infection due to T. rubrum, three of the proteins involved in keratinocyte proliferation and differentiation were significantly affected (K9, K18 had higher levels and caspase 14 levels were decreased)." (PMID 31231322, 2019). "The massive upregulation of caspase-14 early in the infection, a protein involved in keratinocyte differentiation might reflect the rapid onset of epithelial repair mechanisms, and the collagenous stratum compactum seemed to limit the spread of C. shasta within the intestinal layers." (PMID 34578212, 2021).
adenocarcinoma (1 paper, 2022). A common cancer characterized by the presence of malignant glandular cells. "In vitro study evaluating the expression and function of casp-14 in lung, adenocarcinomas suggest that casp-14 is an anti-apoptotic protein targeting apoptosis-inducing factors." (PMID 35777300, 2022).
neurodegenerative disease (1 paper, 2020). A disorder of the central nervous system characterized by gradual and progressive loss of neural tissue and neurologic function. "This “accelerated aging” defect is also suggested by the increased level of caspase 14, a protein involved in apoptosis and of prelamin A/C in CF exosome, as accumulation of lamin proteins, are involved in various neurodegenerative diseases." (PMID 32927759, 2020).
CASP14 also shares sentences with these, for which no sentence is quoted: autosomal recessive congenital ichthyosis (1 paper); bacterial infection (1); basal cell carcinoma (1); bladder cancer (1); clear cell renal cell carcinoma (1); contact dermatitis (1); dermatitis (1); dyskeratosis congenita (1); ectodermal dysplasia (1); hepatocellular carcinoma (1); ichthyosis vulgaris (1); inflammatory bowel disease (1); keratolytic winter erythema (1); legionellosis (1); lung carcinoma (1); lung squamous cell carcinoma (1); neuroblastoma (1); pachyonychia congenita (1); Palmoplantar keratoderma (1); pancreatic cancer (1); peeling skin syndrome 1 (1); peeling skin syndrome 2 (1); peeling skin syndrome 4 (1); pertussis (1); skin infection (1); triple-negative breast carcinoma (1).